NGB (neuroglobin)
Diseases named in the same sentence as NGB in open-access papers (continued):
Sharing a sentence is not in itself a finding about the gene and the disease.
breast carcinoma (continued). "Beyond the well-defined NGB mitochondria-associated function in neuron-derived cells, our previous data clearly show that E2 re-localized the NGB to the mitochondrial compartment also in breast cancer cell models (MCF-7, T47D), making the globin able to exert its anti-apoptotic activities." (PMID 34440755, 2021). "Moreover, immunohistochemical analysis of G2 breast cancer tissues revealed strong NGB staining near the border of the duct close to the lumen, sustaining the idea of a possible accumulation of NGB on the cell periphery." (PMID 34440755, 2021). "Recently, the co-localization of NGB with collagen I fibers at the extracellular levels has been reported in breast tissues, supporting the idea of an in vivo secretion of the protein to the extracellular matrix by breast cancer cells." (PMID 34440755, 2021). "The absence of any association between NGB accumulation in breast cancer tissues and other estrogen receptors (e.g., ERβ and GPER) strongly sustains the results obtained in cancer cell lines confirming the pivotal involvement of the ERα/AKT pathway in NGB accumulation in breast cancer tissues." (PMID 34440755, 2021). "In addition, our recent findings further identified the ERα/AKT/NGB pathway as a common pro-survival process activated in different, ERα-positive, breast cancer cells." (PMID 34440755, 2021). "Overall, our results converge on the accumulation of NGB as a novel characteristic of ERα+ ductal carcinoma of Grade 3 that could be used for improving prognostication and treatment decisions for breast cancer patients." (PMID 34440755, 2021). "Taken together, these results reveal strong evidence of similarities between NGB behavior in the cancer cells’ system and primary breast cancer tissues, strengthening the idea that NGB represents a compensatory protein, which allows cancer cells to survive in an unfavorable environment." (PMID 34440755, 2021). "Furthermore, recent results have clearly indicated that high level of intracellular NGB protein exerts a critical role in the E2, ERα-dependent, antioxidant, and pro-survival effects on breast cancer cells." (PMID 32872414, 2020). "In this context, here, we were aimed at investigating the possibility that NGB could be extracellularly released by breast cancer cells to exert putative exogenous functions on cancer cells phenotype." (PMID 32872414, 2020). "Indeed, NGB represents the key intracellular mediator of E2 antioxidant and pro-survival effects in ERα+ breast cancer cells." (PMID 32872414, 2020). "Thus, NGB upregulation is one of the critical mechanisms triggered by the E2/ERα complex to protect breast cancer cells against oxidative stress by preventing, at mitochondrial levels, the triggering of the apoptotic cascade." (PMID 31354909, 2019). "In addition, E2-dependent up-regulation of NGB results pivotal in the hormone induced overexpression of Bcl-2 protein in breast cancer cell line." (PMID 29216269, 2017). "Although studies more detailed are requested to define the ROS-induced pathways and their functional outcomes, the data reported in this study enlarge the physiological role of NGB in breast cancer cells pointing to its up-regulation as possible ROS sensor as reported in brain-derived cells." (PMID 27149623, 2016). "As hypoxic and oxidative stress injury frequently occurs in fast proliferating neoplastic tissues, here, the effect of these stressors on the level, localization, and anti-apoptotic function of NGB in wild type and NGB-stable-silenced MCF-7 breast cancer cells has been assessed." (PMID 27149623, 2016). "Consequently, ROS and ROS-generating compounds induce high level of oxidized NGB that increase, for example, NGB activity as free radical scavenger supporting the role of NGB as a compensatory protein in breast cancer cells." (PMID 27149623, 2016).
breast carcinoma (continued). "Furthermore, the herein reported results open a new scenario over NGB’s role in breast cancer cells, providing evidence of its possible involvement in further critical cellular processes, including cytoskeleton dynamics and extracellular microenvironment shaping." (PMID 33924212, 2021). "MFC-7 breast cancer cells were stimulated with three concentrations of the RSV analogs (i.e., 0.1, 1.0, and 10.0 μM) for 24 h, and the levels of NGB were evaluated." (PMID 36768470, 2023). "Endogenous NGB was proved to be a ROS-inducible protein in MCF-7 cells and a key factor for E2-induced breast cancer progression." (PMID 33924212, 2021). "The increase in NGB levels induced by E2, via ERα and AKT activation, plays an anti-apoptotic effect when the globin is accumulated into the mitochondria of breast cancer cells." (PMID 34440755, 2021). "In such a context, we found a new compensatory protein named neuroglobin (NGB), which is up-regulated and re-allocated to mitochondria by E2 in ERα+ breast cancer cells." (PMID 34440755, 2021). "Here, we report the quantitative changes in the proteome of ERα-positive human breast cancer cells (namely, the MCF-7 cell line) with the NGB gene knocked out using CRISPR/Cas9 technology." (PMID 33924212, 2021). "Mounting interest in NGB function has recently been growing in non-neuronal compartments and tissues, such as breast cancer cells, highlighting the antioxidant and prosurvival functions of E2-induced NGB expression." (PMID 33924212, 2021). "We recently defined Neuroglobin (NGB), a heme-protein, as a compensatory protein in the 17β-Estradiol (E2) anti-apoptotic activity and as a sensor of oxidative stress in both neurons and breast cancer cells." (PMID 29216269, 2017). "Neither 24 h nor 48 h (data not shown) of physiological hypoxia (2% O2) increases NGB protein levels in comparison to normoxia (21% O2) in breast cancer cells." (PMID 27149623, 2016). "Interestingly, in ERα-positive breast cancer cells (MCF-7 and T47D), Res acts as an ERα antagonist by reducing the ability of this receptor subtype to activate AKT kinase phosphorylation and reducing NGB levels." (PMID 36982977, 2023). "Despite the reported discrepancies, our previous findings define NGB as an E2-inducible protein in ERα+ breast cancer cell models (MCF-7, T47D, ZR51), which accumulation is part of the E2-induced pathway devoted to the survival of breast cancer against stress injuries of a different nature." (PMID 34440755, 2021). "These processes may take place in breast cancer cells in the absence of NGB, especially when NGB expression is not inducible via the administration of NGB-inducible factors." (PMID 33924212, 2021). "In addition, the effects of extracellular NGB resemble the outcomes reported for conditioned media generated from breast cancer cells treated with H2O2, but not with E2." (PMID 32872414, 2020). "Despite this evidence, our results indicate that 2% O2, which resembles the median pO2 present in breast cancer microenvironment, does not up-regulate NGB levels in MCF-7 cells suggesting that NGB is not required for MCF-7 cell adaptation to hypoxic conditions." (PMID 27149623, 2016). "Although NGB may follow one or more of the different mechanisms of non-classical protein secretion, the finding of NGB in astrocytes-derived exosomes suggests that the exosome-mediated mechanism may be directly involved in the globin release also in breast cancer cells." (PMID 32872414, 2020). "Our data indicate that, unlike E2 that induced NGB overexpression, 1–10 μM D reduced NGB levels under the basal level (i.e., vehicle -treated samples) in both MCF-7 and T47D breast cancer cells." (PMID 31936631, 2020). "The role played by extracellular NGB in enhancing MCF-7 cell antioxidant and pro-survival response has been verified in other ERα+ (T47D) and ERα- (MDA-MB-231) breast cancer cell lines as well as in non-tumorigenic epithelial mammary cells (MCF-10A)." (PMID 32872414, 2020).
neuroblastoma (11 papers, 2014 to 2025). Neuroblastoma (NB) is the most common solid, extracranial childhood tumor. "In a previous study, we demonstrated a neuroprotective activity of overexpressed NGB associated specifically with mitochondrial raft-like microdomains in a human neuroblastoma cell line triggered with the neurotoxin MPP+." (PMID 34943907, 2021). "Very recently, a study using mass spectrometry showed that NGB OE acts as a positive regulator of autophagy in a human neuroblastoma cell line." (PMID 40867117, 2025). "In order to investigate processes promoted by NGB overexpression, here we used a cellular model of neuroblastoma that stably overexpresses an NGB-FLAG protein construct." (PMID 34943907, 2021). "We preliminarily investigated the effects of NGB gene overexpression, stably transfected in a cellular model of human neuroblastoma cells (SH-SY5Y), in the form of a FLAG-tagged protein." (PMID 34943907, 2021). "NGB overexpression in cortical, hippocampal neurons and human neuroblastoma cells protects from hypoxia-induced death, while NGB knockdown in cortical neurons exposes them to hypoxia and oxidative stress." (PMID 34943907, 2021). "To investigate processes promoted by NGB overexpression, we used a cellular model of neuroblastoma stably overexpressing an NGB-FLAG construct." (PMID 34943907, 2021). "NGB has been found upregulated by ischemia/hypoxia in cultured cell lines and primary mouse cortical neurons and by oxidative stress in neuroblastoma cell." (PMID 29216269, 2017). "Sp1 and NF-kB transcription factor binding sites are present on NGB promoter and their binding is demonstrated in neuroblastoma cell lines." (PMID 27313512, 2016). "Suppression of the activity of caspase-3 and caspase-9 by NGB overexpression was also observed in human neuroblastoma SH-SY5Y cells undergoing BH3 mimetic-induced apoptosis or amyloid-β toxicity." (PMID 27809238, 2016). "A promising approach involves 17β-estradiol (E2) which was found to upregulate NGB in neuroblastoma cells, in mouse primary hippocampal neurons and in primary astrocytes at physiological concentrations (~1 nM)." (PMID 27809238, 2016). "Another transcription factor that mediates ERα binding is cAMP response element-binding protein (CREB), bound on mouse NGB promoter in N2a neuroblastoma cells." (PMID 27313512, 2016). "E2-induced NGB protein expression in neuroblastoma cell lines, SK-N-BE, has been previously demonstrated and, here we investigated SK-N-BE and NT-2 cells upon conditions leading to cell differentiation." (PMID 27313512, 2016). "NGB modulation upon E2 treatment is mediated by ERβ as demonstrated in human neuroblastoma cell line (SK-N-BE), in mouse primary hippocampal neurons, mouse astrocytes and several cancer cell lines." (PMID 27313512, 2016). "Thus, in neuroblastoma cells exposed to H2O2, the hormone further increases the mitochondrial association of neuroglobin with cytochrome c, preventing its release from the mitochondria to the cytosol and, therefore, the initiation of the apoptotic cascade." (PMID 34440676, 2021). "The comparison of two cell lines from different origin (SK-N-BE, human neuroblastoma cell lines, and NT-2, human embryonal carcinoma cell line) upon differentiation conditions represented models to study E2-induced NGB transcription regulation and find genomic regulatory regions." (PMID 27313512, 2016). "Thus, it has been reported that the synthetic steroid diarylpropionitrile (DPN), a selective agonist of ERβ that exerts neuroprotective actions, induces the expression of neuroglobin in SK-N-BE neuroblastoma cells, while propyl pyrazole triol (PTT), a selective agonist of ERα, does not." (PMID 34440676, 2021). "In terms of its molecular mechanism of action against neuroblastoma tumors, DpC significantly increased levels of phosphorylated JNK, neuroglobin, cytoglobin, and cleaved caspase 3 and 9, while simultaneously decreasing inhibitory IĸBα levels in vitro." (PMID 27678372, 2016).
Alzheimer disease (10 papers, 2010 to 2023). A progressive, neurodegenerative disease characterized by loss of function and death of nerve cells in several areas of the brain leading to loss of cognitive function such as memory and language. "Neuroglobin (NGB) gene expression is associated with neural disease (Alzheimer’s Disease) when the GATA2 TF works to regulate the NGB gene expression." (PMID 37993790, 2023). "In other cases of brain dysfunction neuroglobin has been shown to attenuate beta-amyloid neurotoxicity and Alzheimer’s disease, showing genetic association and gene expression changes associated with Alzheimer’s dementia." (PMID 24710547, 2012). "The neuroprotective role of neuroglobin has been shown both in vitro and in vivo, and its decreased expression has been associated with increased risk of Alzheimer’s disease." (PMID 20640154, 2010). "Several studies have associated genetic polymorphisms within the human neuroglobin gene with neuroprotection, and decreased expression of neuroglobin in older people, in women, or associated with single nucleotide polymorphism has been linked to increased risk of Alzheimer’s disease." (PMID 20640154, 2010). "In the nervous system, overexpression of NGB protected neurons against mitochondrial dysfunction and neurodegenerative diseases such as Alzheimer's disease as well as acting as a shield in cancer cells." (PMID 37005662, 2023). "On the other hand, the expression of neuroglobin declines in the brain in Huntington’s disease mouse model and in Alzheimer’s disease patients in parallel to the increase in pathological alterations." (PMID 34440676, 2021). "NGB was shown to diminish beta-amyloid-induced neurotoxicity in vitro and to attenuate the phenotypes in a transgenic mouse model of Alzheimer’s disease and to act as an oxidative stress-responsive sensor for neuroprotection." (PMID 27341336, 2016). "However, the observation of a drop in NGB plasma levels in individuals who have progressed from cognitive normal to MCI -which we assume reflects a drop in brain levels-, together with the mice data would imply that NGB is a defensive mechanism during the early phases of Alzheimer’s disease." (PMID 33343276, 2020). "In addition, neuroglobin overexpression protects neuronal cells from NMDA and β-amyloid toxicity and decreases behavioral deficits in mice with Alzheimer’s disease." (PMID 34440676, 2021).
Cerebral ischemia (10 papers, 2005 to 2026). Restriction of arterial blood supply to the brain associated with insufficient oxygenation to support the metabolic requirements of the tissue. "A recent study showed that early serum neuroglobin concentration predicts delayed cerebral ischemia in patients with aneurysmal subarachnoid hemorrhage." (PMID 35463129, 2022). "Although promising, most studies using neuroglobin delivery approaches have been performed on brain ischemia in vivo and in vitro models, demonstrating the urgent need to implement these approaches for other brain diseases." (PMID 34440676, 2021). "Neuronal hypoxia and cerebral ischemia increase NGB levels that protect against neurodegeneration because NGB silencing induces neuron apoptosis." (PMID 27313512, 2016). "In the present study, the necrotic zone produced by cerebral ischemia was characterized, demonstrating an increase in the number of hyperchromatic cells and NGB-positive cells in cortical tissues." (PMID 25847303, 2015). "Neuroglobin-immunoreactive material was upregulated in the cytoplasm of neurons that were destined to survive acute cerebral ischemia, and was reduced in apoptotic neurons." (PMID 15730566, 2005). "Surprisingly, 83.13% of babies had NGB concentrations higher than the putative 8.4 ng/mL value, recently hypothesized as a prognostic cut-off between good and bad recovery from cerebral ischemia in adults." (PMID 40715242, 2025). "We hypothesized that if neuroglobin is directly involved in neuroprotection, then permanent cerebral ischemia would lead to larger infarct volumes in neuroglobin-null mice than in wild-type mice." (PMID 22901501, 2012). "Moreover, the fact that vascular endothelial growth factor (VEGF) stimulates neuroglobin through VEGFR2/Flk1 may also suggest the involvement of neuroglobin in neovascularization and angiogenesis, two essential repairing cellular mechanisms that are severely disturbed in cerebral ischemia." (PMID 34440676, 2021).
ischemia (6 papers, 2005 to 2018). A hypoperfusion of the BLOOD through an organ or tissue caused by a PATHOLOGIC CONSTRICTION or obstruction of its BLOOD VESSELS, or an absence of BLOOD CIRCULATION. "For example, neuroglobin expression was 4 times higher in the cerebral cortex than the hippocampus, corresponding to the time for ischemia to cause half-maximal damage (19.1 and 12.7 min, respectively) in these tissues." (PMID 15730566, 2005). "It has been reported that neuroglobin (Ngb) is upregulated in response to hypoxia-ischemia insults and exhibits a protective role in ischemia-reperfusion brain injury." (PMID 29922222, 2018). "Neuroglobin over expression resulted in a significant reduction in infarct volume 24 hours after ischemia." (PMID 24098534, 2013). "Neuroglobin expression was inversely correlated to the sensitivity of the brain regions to ischemia." (PMID 15730566, 2005). "Neuroglobin was initially discovered in neurons as a 150 amino acid-long heme-protein displaying <25% sequence identity to conventional vertebrate hemoglobin or myoglobin, and neuroglobin was shown to protect neuron from several neurotoxic conditions such as ischemia in vivo and in vitro." (PMID 25815107, 2015). "This suggests no selective sparing of neuroglobin expressing neurons in ischemia." (PMID 22901501, 2012).
glaucoma (4 papers, 2012 to 2021). Increased pressure in the eyeball due to obstruction of the outflow of aqueous humor. "One group investigated an AAV vector encoding NGB (AAV2-NGB) in the DBA/2J mouse model of glaucoma." (PMID 33920974, 2021). "As RGC count improvement required early treatment, and early glaucoma being relatively asymptomatic, the temporal factor would make NGB a difficult gene therapy strategy to use in clinical applications." (PMID 33920974, 2021). "The neuroglobin protein has been shown to be protective in retinal ischemia and also in the case of glaucoma." (PMID 24710547, 2012). "Among them, the increase in NGB levels in both retina and plasma of patients with advanced chronic glaucoma has been reported proposing the high globin expression as a biomarker of glaucoma disease." (PMID 34831423, 2021). "On the other side, a plasma NGB downregulation in patients with diabetic retinopathy has been reported suggesting the use of NGB as an inverse biomarker with respect to what is observed in glaucoma." (PMID 34831423, 2021). "In the mice model of glaucoma induced by experimental ocular hypertension, NGB-induced RGCs survival was not correlated with the preservation of visual pathway." (PMID 34831423, 2021). "Furthermore, in glaucoma mice models characterized by the genetic (DBA/2J mice) or experimental induction of intraocular hypertension, the tight connection between NGB mitochondrial location and neuroprotective effect has been demonstrated." (PMID 34831423, 2021).
carbon monoxide poisoning (3 papers, 2005 to 2022). A poisoning that is caused by exposure to carbon monoxide. "I.v. administration of a high-affinity carbon monoxide–binding (CO-binding) molecule, recombinant neuroglobin, can improve survival in CO poisoning mouse models." (PMID 36173682, 2022). "That this is a reasonable therapeutic approach comes from the recent demonstration that systemic administration of a recombinant NGB, with higher oxygen binding affinity and higher NO reduction capacity, is effective to prevent carbon monoxide poisoning." (PMID 33343276, 2020). "Neuroglobin may also play a protective role in carbon monoxide poisoning." (PMID 15730566, 2005).